JAK3 (Janus kinase 3)
Diseases named in the same sentence as JAK3 in open-access papers (continued):
Sharing a sentence is not in itself a finding about the gene and the disease.
severe combined immunodeficiency (52 papers, 2006 to 2026). Severe combined immunodeficiency (SCID) comprises a group of rare monogenic primary immunodeficiency disorders characterized by a lack of functional peripheral T lymphocytes resulting in early-onset severe respiratory infections and failure to thrive. "In the context of immunodeficiencies, inherited mutations in JAK3 are associated with severe combined immunodeficiency (SCID), while PBMC mutations are linked to autosomal recessive hyperimmunoglobulin E syndrome." (PMID 41153712, 2025). "One was an IL2RB1 gene mutation that leads to susceptibility to tuberculosis, and the other was a JAK3 gene mutation that is associated with severe combined immunodeficiency and a STAT1 gene mutation that also increases susceptibility to tuberculosis." (PMID 38678116, 2024). "The role of JAKs in the pathophysiology of diseases was first demonstrated in 1995 with the identification of a loss-of-function mutation in JAK3 in severe combined immunodeficiency (SCID)." (PMID 34532638, 2021). "In human, mutations in Jak3 related severe combined immunodeficiency disease feature reduction of immune cells such as T cells and NK cells." (PMID 33814980, 2021). "Janus kinase 3 (JAK3) tyrosine kinase has a central role in the control of lymphopoiesis, and mutations in JAK3 can lead to either severe combined immunodeficiency or leukemia and lymphomas." (PMID 30560087, 2018). "Genetic analysis revealed that our patient had 2 novel compound heterozygous mutations of JAK3, a gene previously reported to cause a rare form of autosomal recessive severe combined immunodeficiency with recurrent infections." (PMID 29049190, 2017). "JAK3 interacts with many inflammatory cytokines through the common γ chain receptor subunit, and inactivating mutations in the common γ chain and JAK3 have been shown to cause X-linked severe combined immunodeficiency." (PMID 28451787, 2017). "In humans, JAK3 deficiency is associated with severe combined immunodeficiency (SCID), which is characterized by profound defects in T- and NK-cell development." (PMID 24170986, 2013). "In particular, mutations of the IL7R α chain, or the γc chain, or its associated kinase, JAK3, are the major causes of human severe combined immunodeficiency (SCID)." (PMID 16907989, 2006). "Similarly, analysis of mutations in Jak3 that are associated with severe combined immunodeficiency suggests that they compromise Jak3 function by destabilizing the FERM-SH2 structure." (PMID 27227461, 2016). "Mutations of the Janus family kinase JAK3 gene cause severe combined immunodeficiency (SCID)." (PMID 26321643, 2015). "The potential for IS by JAK3 inhibitors was discovered serendipitously by the observation gamma-chain mutations of JAK3 were associated with severe combined immunodeficiency in humans, a condition associated with non functional B cells and an absence of T cells and natural killer (NK) cells." (PMID 20130772, 2009). "A landmark discovery in 1995 identified loss-of-function (LOF) variants in JAK3 as the cause of Severe Combined Immunodeficiency (SCID), illustrating the crucial role of the JAK family in lymphoid development." (PMID 41136770, 2025). "JAK3 knock-out mice are found to develop severe combined immunodeficiency (SCID) due to impairment in B cell development associated with IL-2, IL-4, IL-7, IL-9, and IL-15 receptor signaling." (PMID 38380328, 2024). "JAK3 mediates signals from type 1 cytokines and thus deficiency of JAK3 lead to severe combined immunodeficiency (SCID)." (PMID 38979496, 2024). "Severe chronic HPV disease is associated with severe combined immunodeficiency (SCID) caused by IL2RG (interleukin 2 receptor subunit γ) or JAK3 deficiency." (PMID 36960048, 2023). "As a form of severe combined immunodeficiency (SCID), Janus kinase 3 (JAK3) deficiency can be fatal during severe infections in children, especially after inoculation of live-attenuated vaccines." (PMID 36466884, 2022).
severe combined immunodeficiency (continued). "Mutations that abrogate Jak3 functions cause an autosomal severe combined immunodeficiency disease (SCID) while activating Jak3 mutations lead to the development of hematologic and epithelial cancers." (PMID 33814980, 2021). "In severe combined immunodeficiency (SCID) resulting from mutations in JAK3, T cells were obviously decreased." (PMID 34925323, 2021). "We also use the Jak2 structure to demonstrate how Jak3 mutations identified in patients result in severe combined immunodeficiency (SCID)." (PMID 27227461, 2016). "Furthermore, mutations which abrogated JAK3 might cause an autosomal SCID (severe combined immunodeficiency disease)." (PMID 24674592, 2014). "The importance of JAK3 in IL-2 signaling has been further substantiated by the recent findings that homozygous point mutations or deletions of the Jak3 gene are found in autosomal recessive T-B+ severe combined immunodeficiency patients as well as immunocompromised mice." (PMID 21647403, 2011). "JAK3 is principally activated by members of the interleukin-2 receptor family and plays an essential role in lymphoid development, with inactivating JAK3 mutations causing autosomal-recessive severe combined immunodeficiency (SCID)." (PMID 36291730, 2022). "An autosomal severe combined immunodeficiency (SCID)-associated mutation, Y100C, is located in the hydrophobic core of the JAK3 FERM domain." (PMID 28458652, 2017). "JAK3 knockout mice show defective signaling of IL-2, IL-4, IL-7, IL-9 and IL-15 and suffer from severe combined immunodeficiency, as do patients with genetic defects in JAK3." (PMID 26938566, 2016). "Genetic defects in IL2RG or JAK3 can cause the phenotype of severe combined immunodeficiency (SCID) with absent T- and non-functional B-lymphocytes (T-B+ SCID)." (PMID 41863562, 2026). "In the Janus kinase 3 (JAK3) gene, the variant c.1333C>T, p.Arg445Ter was detected, which has been reported as a pathogenic variant in severe combined immunodeficiency but has not yet been reported in RA." (PMID 38473001, 2024). "The mutation (c.2652 C > T; pV884V) in JAK3 exon 19, which has been identified in patients with severe combined immunodeficiency (SCID), did not encode an altered the amino acid sequence but created a new 5’ss73." (PMID 37009804, 2023). "X-linked severe combined immunodeficiency and JAK3 deficiency are characterized by a lack of T and NK cells but normal or increased numbers of B cells." (PMID 24600453, 2014). "Abnormal JAK3 signal transduction can manifest as hematological disorders, e.g., leukemia, severe combined immunodeficiency (SCID) and autoimmune disease states." (PMID 37569303, 2023). "The most extreme syndrome of lymphocyte dysfunction, severe combined immunodeficiency (SCID), arises from mutations in a number of genes: IL2RG, RAG1, RAG2, ADA, JAK3, and IL7RG." (PMID 36839582, 2023). "JAK3 gene variants can lead to autosomal recessive severe combined immunodeficiency (SCID), which is T-cell-negative, B-cell-positive, and NK-cell-negative (OMIM: 600802)." (PMID 40225147, 2023). "Patients with severe combined immunodeficiency (SCID) caused by LOF mutations of IL2RG or JAK3 who undergo hematopoietic stem cell transplantation do not reconstitute a normal pool of peripheral ILC and NK cells." (PMID 36736301, 2023). "Combining the clinical features and genetic analysis results, the infant was finally diagnosed as severe combined immunodeficiency (SCID) with T-cell-negative, B-cell-positive, and NK-cell-negative findings caused by JAK3 function defection." (PMID 40225147, 2023). "Similarly, to investigate JAK3 function in autoimmune diseases, a CRISPR-Cas9-mediated JAK3 deletion was generated in an induced pluripotent stem cell (iPSC) line derived from a patient with severe combined immunodeficiency (SCID)." (PMID 36232600, 2022).
severe combined immunodeficiency (continued). "The classical example is severe combined immunodeficiency (SCID) with defects in T cells, B cells, and NK cells caused by defects in IL2RG, RAG1/2, ADA, JAK3, and IL7R genes, in which an increased risk of disseminated VZV infection has been well-recognized for many years." (PMID 32495195, 2020). "For example, mutant Jak1 and Jak3 mice have severe combined immunodeficiency (SCID), and Jak1 mutants also have neurological defects and poor survival past birth; knock out mutations in Jak2 are embryonic lethal, and mutations in the Jak family member Tyk2 result in poor response to pathogens." (PMID 30558204, 2018). "Mutations in the Janus Kinase 3 (JAK3) gene cause an autosomal recessive form of severe combined immunodeficiency (SCID) usually characterized by the absence of both T and NK cells, but preserved numbers of B lymphocytes (T‐B+NK‐SCID)." (PMID 30032486, 2018). "The first inferred gene is a functional immune cell specifically expressed gene JAK3 (ENSP00000391676) and is pathologically related to autosomal severe combined immunodeficiency disease." (PMID 30349554, 2018). "In contrast, inactivating JAK3 mutations cause autosomal-recessive severe combined immunodeficiency (SCID) in humans, characterized by a lack of T and Natural Killer (NK) cells and non-functional B cells, due to loss of function for the relevant cytokine receptors." (PMID 36291730, 2022). "In contrast, humans and mice lacking Jak3 present with a distinct primary immunodeficiency disorder designated T-B+NK- severe combined immunodeficiency (SCID)." (PMID 21861931, 2011). "Mutations in genes that affect the development or function of T and B cells [DCLRE1C(ARTEMIS), ZAP70, RAG1/2, IL2RG, ILRA7, LIG4, JAK3, ADA] can result in intestinal inflammation along with recurrent infections from severe combined immunodeficiency (SCID)." (PMID 34122435, 2021). "The engraftment rate increases with the introduction of Non-obese diabetic Severe combined immunodeficiency (NOD/SCID)-based immunocompromised mice, especially the NK-deficient NOD strains NOD/SCID/interleukin-2 receptor gamma chain(IL2Rγ)null (NOG/NSG) and NOD/SCID/Jak3(Janus kinase 3)null (NOJ)." (PMID 31412684, 2019).
Immunodeficiency (50 papers, 2010 to 2026). Failure of the immune system to protect the body adequately from infection, due to the absence or insufficiency of some component process or substance. "For example, inactivating mutations in JAK3 can cause severe combined immunodeficiency (SCID), while loss-of-function mutations in TYK2 result in milder immunodeficiency." (PMID 40264772, 2025). "IL2rg and JAK3 mutations were introduced into NOD‐SCID mice in order to further enhance immune deficiency in the mice." (PMID 38591343, 2024). "JAK2 and JAK3 are expressed in epithelial and hematopoietic cells, and their deficiency results in hematological disorders, including immunodeficiency." (PMID 38990897, 2024). "JAK3 LOF mutations cause an autosomal-recessive form of severe combined immune deficiency (SCID), comprising approximately 5% of total SCID." (PMID 38474223, 2024). "This suggests that the immunodeficiency caused by JAK3 mutation significantly impacts tumor immunity." (PMID 36291730, 2022). "Jak3 mediates signals initiated by the cell surface receptors, and Jak3-deactivating mutations lead to severe combined immunodeficiency." (PMID 36145091, 2022). "Mutations in the JAK3 gene leads to severe combined immunodeficiency in humans and mice due to a disturbed T- and B-lymphocyte development and function." (PMID 34022808, 2021). "Nevertheless, the majority of patients with defective Jak3 are associated with severe combined immunodeficiency and thus compounding effects due to increased susceptibility to infection cannot be easily excluded." (PMID 33584707, 2020). "Jak3 mutation in humans leads to severe combined immunodeficiency and studies using Jak3−/− mice further confirmed the critical role of Jak3 in lymphoid development." (PMID 31447854, 2019). "The first JAK-linked disease discovered was the severe combined immune deficiency (SCID) which was characterized by NK cell abnormalities caused by LOF JAK3 mutations." (PMID 30671064, 2018). "Disruption of interleukin (IL)-15/STAT5 signaling pathway due to the loss of IL-15 receptor chains, JAK3 or STAT5 leads to immune deficiencies with natural killer (NK) cell abnormalities." (PMID 30671064, 2018). "Mutations inactivating Jak3 functions lead to immunodeficiency, and its abnormal activation is associated with different malignancies." (PMID 28821617, 2017). "Deficiency/defects in JAK3 leading to low amounts of functional protein are associated with immune dysfunction/immunodeficiency." (PMID 28359267, 2017). "Accumulation of CD62LlowCD44high T cells in peripheral lymphoid organs has been observed in various immunodeficiencies, including Jak3- and common cytokine receptor γ chain (γc)-deficient mice." (PMID 24852423, 2014). "We here present the first case of revertant mosaicism in JAK3 deficiency, manifesting as combined immunodeficiency evolving into predominant CD4+ lymphopenia." (PMID 25205547, 2014). "Similarly, NOD/SCID/Jak3null mice, or NOJ mice, exhibit comparable immune deficiencies due to Janus kinase 3 (Jak3)'s role in IL2Rγ signaling." (PMID 41141391, 2026). "However, rare mutations in JAK3 have been reported to cause a clinical manifestation of severe immunodeficiency." (PMID 40763733, 2025). "For instance, improper inhibition of JAK2 might cause thrombocytopenia and anemia; improper inhibition of JAK3 might cause immunodeficiency and infection." (PMID 40746612, 2025). "Dysregulation of JAK3 signalling, either through gain-of-function mutations or constitutive activation, has been implicated in a variety of immune disorders and malignancies, including acute lymphoblastic leukemia, T-cell prolymphocytic leukemia, cutaneous T-cell lymphoma, and certain solid tumors." (PMID 41385500, 2025). "The janus kinase 3 (JAK3) gene plays essential roles in the immune system, such as in the function and maturation of B and T-cells, and mutations in this gene were associated with severe combined immune deficiency in humans." (PMID 38397178, 2024).
Immunodeficiency (continued). "The inactivated mutation of JAK3 can lead to immune deficiency." (PMID 32530555, 2020). "However, loss-of-function mutations in JAK3 in humans or experimental deletion of either one of these in mice results in severe combined immunodeficiency." (PMID 33343569, 2020). "However, reports on human TYK2 deficiency show a less severe immunodeficiency phenotype compared to JAK3 deficiency." (PMID 30353145, 2018). "This statement suggests that the activation of receptor complex {IL7R, IL2RG} may activate {JAK1, JAK3} to cause immunodeficiency disease." (PMID 27819359, 2016). "Recently, a case of cryptococcosis was also reported in the setting of HyperIgM syndrome and in a patient with a known “Jak3” gene mutation with severe combined immunodeficiency, raising an alert for physicians managing patients with primary immunodeficiencies." (PMID 29376920, 2015). "The fact that JAK3 deficient mice exhibit profound T cell impairment and JAK3 deficient patients exhibit severe combined immunodeficiency has led to an intense effort to identify inhibitors with specificity for JAK3 as unique immunosuppressive therapeutic agents." (PMID 24603870, 2014). "Looking forward, this approach can be extended to experimental validation, structure–activity optimization, and clinical translation, offering a scalable pathway for developing next-generation therapeutics targeting JAK3-driven cancers and immune disorders." (PMID 41385500, 2025). "For example, lymphoedema is also seen in some cases of Interleukin 2 Receptor Subunit Gamma (IL2RG)/Janus Kinase 3 (JAK3) severe combined immunodeficiency, in which a primary lymphopoietic disorder appears to modify lymphangiogenesis." (PMID 34916230, 2023). "The most frequent main genetic causes of cellular and humoral immunodeficiencies in children infected with SARS-CoV-2 were DOCK8 deficiency (n = 6), IL2RG (n = 5), RelB deficiency (n = 3), JAK3 deficiency (n = 3), and IL7Ra deficiency (n = 3)." (PMID 37559153, 2023). "In particular, JAK3 can be a suitable drug target to treat adaptive immune disorders, considering that JAK3 kinases are produced in specific cells such as hematopoietic cells and lymphocytes." (PMID 36569926, 2022). "The hub genes of this gene set were all critical genes involving the T cell signaling (LCK), antigen translocation (TAP1), and immunodeficiency diseases (JAK3 and RAG1)." (PMID 36180885, 2022). "Jak3 knockout mouse model showing Il-2, Il-4, Il-7, Il-9, and Il-15 conduction defects, elevated levels of Il-6 and Il-17a and severe immunodeficiency, defects in barrier function lead to Ulcerative colitis (UC)." (PMID 33777833, 2021). "Jak3–/– mice have been demonstrated to experience profound immunodeficiency, with developmental defects in various immune cell types, including T cells (both αβ and γδ T cells), B cells, and NK cells." (PMID 33584707, 2020). "Gain‐ or loss‐of‐function mutations in Janus kinase 3 (JAK3) contribute to the pathogenesis of various haematopoietic malignancies and immune disorders, suggesting that aberrant JAK3 signalling is an attractive therapeutic target to treat these disorders." (PMID 32558259, 2020). "The combination of both mutations correlates with immunodeficiency associated with lymphadenopathy, autoimmunity, and hypogammaglobulinemia, whereas carriers of either the CTLA-4 or the JAK3 single mutations are healthy." (PMID 29375547, 2017). "Mutations that impact JAK3 activity have been identified in a number of human diseases, including somatic gain-of-function (GOF) mutations associated with immune cell malignancies and germline loss-of-function (LOF) mutations associated with immunodeficiency." (PMID 38474223, 2024). "This study may provide a valuable reference for the discovery of novel JAK3 inhibitors for those patients with immune diseases." (PMID 35628248, 2022).
Immunodeficiency (continued). "We, therefore, suggest that the combination of the loss-of-function mutation in CTLA-4 with the gain-of-function mutation in JAK3 directs the differentiation of CD4 T cells into dysfunctional TFH cells supporting the development of lymphadenopathy, hypogammaglobulinemia, and immunodeficiency." (PMID 29375547, 2017). "With this consideration, we have noted the presence of rare variants in other immunodeficiency genes (JAK2, JAK3, IL17RA, IL12RB2, CARD14, and TYK2) in our various patients, which could feasibly contribute to the penetrance and/or differences in the clinical phenotypes of the patients." (PMID 36672844, 2022). "Loss-of-function mutations of JAK3 are associated with severe combined immune deficiency (SCID); similarly, loss-of-function mutations of STAT1 and STAT2 were also found responsible for immunodeficiency, whereas STAT5 deficiency can lead to both immunodeficiency and autoimmunity." (PMID 31443172, 2019). "This simplistic understanding is outdated and instead a new way of thinking about STAT1, STAT3, STAT6, JAK1, and JAK3 LOF and GOF disease in terms of the relationship between immunodeficiency and autoimmunity is developing." (PMID 37140667, 2023). "Human or animals lacking either JAK3 or the common gamma chain (γc) expression display severe combined immunodeficiency disease, indicating the crucial role of JAK3 in T-cell development and the homeostasis of the immune system." (PMID 20149240, 2010).